NPY (neuropeptide Y)
Diseases named in the same sentence as NPY in open-access papers (continued):
Sharing a sentence is not in itself a finding about the gene and the disease.
diabetes (continued). "To test the possibility that associations between NPY SNPs with CAD are mediated through traditional CAD risk factors, we performed multivariable regression in our case-control datasets, using hypertension, dyslipidemia, diabetes, BMI, and smoking as covariates with NPY SNP genotype." (PMID 19119412, 2009). "The induction of diabetes in rats (as in STZ-treated animals) decreased the retinal NPY mRNA levels, as well as the protein levels of NPY and of NPY Y5 receptor." (PMID 31374938, 2019). "We examined the co-localization of VGF with both NPY and α-MSH in the human ARC and examined possible differences between controls and diabetics." (PMID 22808091, 2012). "Discussion of the role played by AgRP neurons in diabetes pathogenesis would be incomplete without acknowledging the 2 additional signaling molecules — neuropeptide Y (NPY) and GABA — that are expressed by and synaptically released from these neurons." (PMID 40371641, 2025). "Cumulatively, under expression of both FAIM2 and NPY have shown strong negative correlation between diabetes and hyper-methylation of both genes which are significant co-morbidity factors in the Indian patient population." (PMID 36329447, 2022). "Factors associated with high CSF SOM concentrations were hypertension (p = 0.004), diabetes (p < 0.0001), low plasma total cholesterol (p = 0.004) and LDL cholesterol (p = 0.002), high CSF NPY concentrations (p = 0.03) and high CSF Aβ1–42 concentrations (p = 0.03)." (PMID 30327597, 2018). "Furthermore, there have been no studies investigating NPY and α-adrenergic co-modulation of vascular control in pre-diabetes." (PMID 23071607, 2012). "The possibility that diabetes increased NPY expression in the CGRP-IR perivascular nerve fibers can be excluded, as the CGRP-IR fibers did not co-label for NPY-IR in PMAs from either control or STZ-LI rats." (PMID 24847201, 2014). "NPY-mediated vascular modulation becomes more pronounced under conditions of elevated SNA; however, to date, studies addressing NPY/Y1R-mediated vascular control in pre-diabetes are lacking." (PMID 23071607, 2012).
Insulin resistance (45 papers, 2012 to 2025). Increased resistance towards insulin, that is, diminished effectiveness of insulin in reducing blood glucose levels. "Beyond being a potent orexigen, NPY action in the brain is reported to cause insulin resistance associated with hyperinsulinemia and reduced glucose uptake by skeletal muscle." (PMID 40371641, 2025). "Genetic polymorphisms of the NPY gene (particullary the rs164147 polymorphism) have previously shown an association with insulin resistance and the development of steatohepatitis (the latter in obese subjects)." (PMID 38542814, 2024). "mTOR-S6K1-mediated phosphorylation of IRS-1, and degradation of IRS-1 and InsR via the proteasomal or lysosomal pathway, respectively, were implicated in the mechanism of insulin-induced insulin resistance in these NPY/AgRP-expressing cells." (PMID 34831343, 2021). "Selective re-expression of NPY in AgRP neurons attenuates the reduced feeding response and reverses the protection from insulin resistance upon optogenetic activation of AgRP neurons in NPY-deficient mice." (PMID 31974377, 2020). "Nevertheless, these data collectively demonstrate that NPY deficiency largely abrogated the profound insulin resistance induced by optogenetic stimulation of AgRP neurons." (PMID 31974377, 2020). "Understanding how factors such as NPY may influence local inflammation is key given that macrophage content and activity within adipose tissue is an important factor for insulin resistance and risk for type 2 diabetes." (PMID 23472120, 2013). "Palmitic acid, one of the most abundant components of PO, was associated with inflammation via the activation of toll-like 2 and 3 receptors (TLR2 and TLR3) and nuclear factor kappa b (NF-κB)-mediated cytokine synthesis, insulin resistance, and NPY expression." (PMID 39125278, 2024). "Prenatal HE exposure increases both food intake and hypothalamic NPY expression, which contribute to weight gain and insulin resistance, so we examined these parameters in fostered mice." (PMID 36699605, 2022). "Excess insulin-induced insulin resistance has been demonstrated in several hypothalamic neuronal models, including NPY/AgRP- and POMC-expressing neurons." (PMID 34831343, 2021). "In our previous study, high maternal estradiol led to insulin resistance and disordered eating in mouse offspring due to decreased insulin receptor and elevated neuropeptide Y expression in the hypothalamus." (PMID 34239542, 2021). "NPY not only modulates insulin secretion, but substantially induces insulin resistance in hepatocytes and adipocytes through Y1R and Y5R." (PMID 33708805, 2021). "It is possible that, in view of the extreme hypoleptinemia and insulin resistance, other orexigenic factor, such as neuropeptide Y, were responsible for this alteration." (PMID 33411809, 2021). "In the hypothalamus, metabolism enhancing TTR expression was upregulated, and the PTPN1 level denoting insulin resistance was downregulated, while NPY, AGRP, POMC, CART levels denoting leptin resistance showed a normalizing trend." (PMID 32943760, 2021). "The proinflammatory cytokine tumour necrosis factor alpha (TNFα) also induces insulin resistance in NPY/AgRP neurons." (PMID 34831343, 2021). "The ability of AgRP neurons to induce insulin resistance depends on the expression of NPY, and the application of NPY in the CNS has been shown to efficiently reduce sympathetic activation of BAT and improve systemic insulin sensitivity." (PMID 33123166, 2020). "Collectively, these experiments demonstrate that NPY expression in AgRP neurons is required for the acute food intake stimulatory and insulin resistance-inducing effects of optogenetic AgRP neuron activation." (PMID 31974377, 2020). "Further, we demonstrate that the acute insulin resistance-inducing effect of both chemogenetic and optogenetic AgRP neuron activation strongly depends on NPY signaling." (PMID 31974377, 2020).
Insulin resistance (continued). "In turn, NPY promotes adipocyte proliferation and differentiation, and long-term NPY overexpression induces adipose tissue insulin resistance." (PMID 33088334, 2020). "Strikingly, selective re-expression of NPY in AgRP neurons in ChR2AgRP; NPYΔ/Δ mice completely restored the induction of insulin resistance upon optogenetic activation of AgRP neurons during an ITT." (PMID 31974377, 2020). "Activation of AMPK in NPY/AgRP neurons has demonstrated a beneficial role in attenuating elevated NPY levels, and plays a preventative role in the induction of insulin resistance with palmitate treatment." (PMID 27893782, 2016). "The euglycemic-hyperinsulinemic clamp assay showed that HFD and NPY overexpressing rats had lower GIR60-120 than LFD rats, which indicated that peripheral insulin resistance was induced in rats fed with HFD or rats overexpressing NPY for 8 weeks." (PMID 25993471, 2015). "In this study we investigated the molecular mechanisms of NPY that contribute to peripheral insulin resistance." (PMID 25993471, 2015). "In summary, this study has demonstrated the establishment of insulin resistance in rats’ adipose tissue, after long-term constitutive overexpression of NPY in the PVN of hypothalamus." (PMID 25993471, 2015). "The mechanism by which NPY contributes to insulin resistance in adipose tissue, therefore, is not well understood." (PMID 25993471, 2015). "In animals, intracerebroventricular administration of NPY is shown to promote hyperphagia, hyperinsulinemia, insulin resistance, and obesity." (PMID 26064978, 2015). "Therefore, the altered gut microbiota composition resulting from surrogate fostering correlated significantly with the correction of insulin resistance, fecal SCFAs, serum intestinal hormones, and hypothalamic NPY." (PMID 36699605, 2022). "Oleate increases insulin signaling and reduces NPY expression and linolenic acid may reduce insulin resistance through the increase in fatty acid oxidation in agreement with our data showing augmented Cpt1a expression in ND IRS2−/− mice." (PMID 34440853, 2021). "Therefore, chronic stress-induced peripheral NPY plays a mechanistic role in the enhanced vulnerability to visceral obesity, insulin resistance and oxidative stress." (PMID 35010951, 2021). "Acutely stimulating AgRP neurons fails to induce systemic insulin resistance in NPY-deficient mice, while increased locomotor activity upon AgRP neuron stimulation in the absence of food remains unaffected in these animals." (PMID 31974377, 2020). "Apart from a sedentary lifestyle and metabolic syndrome, increased fasting neuropeptide Y levels in migraine can also be responsible for insulin resistance (and subsequent glucose metabolism changes) by specific alterations in energy intake and activation of the sympathoadrenal system." (PMID 32089752, 2020). "Additionally, activation of the parasympathetic nervous system by NPY and the abundance of autonomic nerves in adipose tissue may partly explain how NPY directly contributes to the establishment of insulin resistance in adipose tissue in rats." (PMID 25993471, 2015). "Overexpression of NPY in DMH decreased the expression of UCP1 in BAT, leading to insulin resistance; however, the downregulation of DMH NPY improved glucose homeostasis and enhanced insulin sensitivity." (PMID 33123166, 2020). "However, in the present study we have selectively activated AgRP neurons through complementary chemogenetic and optogenetic approaches and detected changes in AgRP-driven food intake and insulin resistance, which we did not detect in the respective NPY proficient and deficient control groups." (PMID 31974377, 2020). "Neuropeptide Y (NPY) and interleukin 1 beta (IL1B) play important roles in insulin resistance and impairment." (PMID 27749914, 2016).
Insulin resistance (continued). "However, HFD failed to induce any obvious change in the phosphorylation of GSK3β in adipose tissue, which implies that the differential phosphorylation of GSK3β may be one important factor to explain a different mechanism of insulin resistance in adipose tissue induced by NPY overexpression and HFD." (PMID 25993471, 2015). "Next, we investigated the ability of chemogenetic AgRP neuron stimulation to induce systemic insulin resistance in the presence or absence of NPY expression." (PMID 31974377, 2020). "After omentectomy, plasma leptin, insulin, NPY, AGRP, and PMCH levels decreased, which may result a decrease in leptin and insulin resistance." (PMID 29367725, 2018). "However, serum insulin levels and HOMA-IR index were increased in NPY and DIO-NPY compared to their control groups suggesting insulin resistance." (PMID 29674968, 2018). "Therefore, in the present study we have compared the ability of chemogenetic and optogenetic AgRP neuron activation to stimulate feeding, as well as to induce insulin resistance and to affect locomotor activity either in the presence or absence of NPY." (PMID 31974377, 2020). "Nevertheless, these studies had not investigated, whether the insulin resistance regulatory role of AgRP neuron activation may depend on functional NPY expression in these neurons." (PMID 31974377, 2020). "Moreover, HOMA-IR test confirmed previous results, demonstrating that rats overexpressing NPY with or without a HFD develop insulin resistance." (PMID 25993471, 2015).
neuroblastoma (39 papers, 2000 to 2025). Neuroblastoma (NB) is the most common solid, extracranial childhood tumor. "Consistent with our finding, others have demonstrated that an AAV1 vector encoding NPY can successfully transduce human SH-SY5Y neuroblastoma cell line in vitro." (PMID 37029201, 2023). "Metastasis has been associated with a high release of NPY from neuroblastoma cells; NPY promoted the motility and invasiveness of these cells, and the peptide acted as a chemotactic factor for neuroblastoma cells." (PMID 37373115, 2023). "In neuroblastoma, a high level of NPY is linked to poor prognosis, and multiple studies have demonstrated that NPY can promote tumor growth in an autocrine manner and induce vascularization through the NPY-mediated Y2 and Y5 receptor signaling pathways." (PMID 34068501, 2021). "We find a highly significant concordance between the peptides empirically detected in the combined ligandome of 16 neuroblastoma tumors carrying various HLA alleles, and the regions of the NPY protein predicted to be most highly presented by HLA across the population." (PMID 32256484, 2020). "In a pediatric malignancy, neuroblastoma (NB), high NPY release from tumor tissue associates with metastatic disease." (PMID 33681186, 2020). "Fate 2, corresponding to cluster cIVS, exhibited increasing expression of neuronal function markers NPY, MAP2, GAP43, and GATA2, which are associated with differentiating neuroblastomas." (PMID 40448172, 2025). "Peptides (angiotensin II, neuropeptide Y, neurotensin, substance P) act as oncogenic agents in neuroblastoma, whereas others (adrenomedullin, corticotropin-releasing factor, urocortin, orexin) exert anticancer effects against neuroblastoma." (PMID 40331938, 2025). "A recent review dedicated on the involvement of neuropeptide Y in cancer development, including neuroblastoma, has been published." (PMID 40331938, 2025). "There is also emerging evidence suggesting that NPY contributes to tumorigenesis in several different cancer types including neuroblastoma (NB), prostate, liver, colon, and breast cancer." (PMID 40073121, 2025). "NPY was also reported in ganglioneuroblastomas; Y1R, Y4R, and Y5R were expressed in SK-N-MC neuroblastoma cells, and Y5R mediated their proliferation." (PMID 37373115, 2023). "The synthesis and release of NPY from neuroblastoma cells are stimulated by the PKC-coupled M3 muscarinic receptor." (PMID 37373115, 2023). "In neuroblastoma, NPY is less processed in tumor tissue, resulting in later clinical staging and poorer prognosis." (PMID 36774376, 2023). "High serum NPY levels correlate with relapse, metastasis, and poor survival in patients with neuroblastoma, and a high Y5R expression has been suggested as a biomarker for angio-invasive cancer cells." (PMID 37373115, 2023). "NPY also protects against endoplasmic reticulum stress and glutamate excitotoxicity in human neuroblastoma SH-SY5Y cells." (PMID 37373115, 2023). "NPY, released from neuroblastoma cells, exerted through Y2R an autocrine action on cancer cells favoring cell proliferation." (PMID 37373115, 2023). "The role of NPY system and its receptors was studied most extensively in pediatric neoplasms—Ewing sarcoma and neuroblastoma." (PMID 36583743, 2023). "NPY and Y2R are expressed in neuroblastoma cells, and NPY, released from these cells, favored cancer cell proliferation and angiogenesis in an autocrine manner." (PMID 37373115, 2023). "NPY, released from neuroblastoma cells, favored cancer cell proliferation and the vascularization of tumors, which were counteracted with Y2R antagonists but not with Y5R antagonists." (PMID 37373115, 2023). "ProNPY processing has been associated with inferior outcomes/clinically advanced stages in neuroblastoma; thus, the proNPY to NPY processing degree was lower in advanced neuroblastomas with metastatic or regional spread." (PMID 37373115, 2023).
neuroblastoma (continued). "NPY increases cell survival, restores the level of neurotrophins, and counteracts the toxic action mediated by β-amyloid in neuroblastoma cells (SH-SY5Y)." (PMID 37373115, 2023). "Results from in vitro studies had suggested that the potent pro-absorptive peptide neuropeptide Y (NPY) was altered after OA treatment in a neuroblastoma cell line." (PMID 35323497, 2022). "The high expression of NPY matches up with poor prognosis in patients with neuroblastoma and prostate cancer." (PMID 36081667, 2022). "Another 36-amino-acid-long peptide is Neuropeptide Y. The elevated plasma levels of NPY have mostly been the focus of research in pheochromocytomas, neuroblastomas and gangliomas." (PMID 36233409, 2022). "Using SH-SY5Y neuroblastoma cells as a model, we induced stress to simulate cellular neurodegeneration and co-treated with NPY to investigate its protective effects." (PMID 36429093, 2022). "The present study aimed to elucidate the protective effects of NPY against glutamate toxicity and tunicamycin-induced ER stress in the human neuroblastoma SH-SY5Y cell line." (PMID 36429093, 2022). "Groups of enlarged, NPY-positive neuroblastoma cells were extending between necrotic areas and blood vessels in tumor tissues derived from TH-MYCN mice, which spontaneously develop neuroblastoma." (PMID 35484119, 2022). "In this study, we have investigated the protective role of NPY against glutamate toxicity and ER stress in human neuroblastoma SH-SY5Y cells and determined its role in downregulating cellular pro-apoptotic events." (PMID 36429093, 2022). "An SH-SY5Y neuroblastoma cell line was exposed to toxic concentrations of Aβ25-35 peptide fragment (Aβ25-35), and neurotrophin expression was measured before and after NPY preincubation." (PMID 34344469, 2021). "Previous studies have also shown an impairment of NPY production on SH-SY5Y neuroblastoma cell line when treated with OA." (PMID 34148100, 2021). "Based on these results paired with the high level of differential expression, and its role in promoting tumor growth, we suggest that NPY is a promising candidate for vaccine development for neuroblastoma patients." (PMID 32256484, 2020). "In vitro, the permeability of an IEC monolayer was affected by OA through the secretion of neuropeptide Y by neuroblastoma cells." (PMID 31340532, 2019). "In other studies, NPY was shown to be frequently hypermethylated in neuroblastomas, hepatocellular carcinoma tissues and their promoter hypermethylation was correlated with inactivation of gene expression." (PMID 24289328, 2013). "We also studied the effects of intermittent hypoxia on the differentiation status of neuroblastoma cells by examining the expression of the sympathetic neuronal peptide neurotransmitter gene, NPY." (PMID 22363512, 2012). "NPY favors tumor cell growth, migration, and metastasis and promotes angiogenesis in some tumors (e.g., breast cancer, colorectal cancer, neuroblastoma, pancreatic cancer), whereas in others it exerts an antitumor effect (e.g., cholangiocarcinoma, Ewing sarcoma, liver cancer)." (PMID 37373115, 2023). "Serum NPY level has been suggested as a biomarker for neuroblastoma." (PMID 37373115, 2023). "NPY blocked Ca++ channel currents in human neuroblastoma cells (SH-SY5Y)." (PMID 37373115, 2023). "Moreover, under pro-apoptotic conditions, NPY/Y5R was upregulated in neuroblastoma cells (in a BDNF-independent manner)." (PMID 37373115, 2023). "A lower proNPY processing to NPY has been associated with poor outcome/clinical advanced stages in neuroblastoma, and it has been suggested that NPY expression is not correlated with malignancy in pheochromocytomas." (PMID 37373115, 2023). "The same phenomenon was observed in neuroblastoma, another NPY-rich tumor expressing Y5R." (PMID 35484119, 2022). "In neuroblastoma and Ewing sarcoma NPY stimulates proliferation and modulates angiogenesis." (PMID 34277455, 2021).